COL5A2 (collagen type V alpha 2 chain)
Diseases named in the same sentence as COL5A2 in open-access papers (continued):
Sharing a sentence is not in itself a finding about the gene and the disease.
osteosarcoma (15 papers, 2020 to 2025). A usually aggressive malignant bone-forming mesenchymal neoplasm, predominantly affecting adolescents and young adults. "Multi-factorial COX regression analysis of four genes in the risk model related to the prognosis of osteosarcoma led to the identification of COL5A2 as the key gene associated with osteosarcoma prognosis." (PMID 35280775, 2022). "COL5A2 may be associated with the aggressiveness and metastasis of osteosarcoma, affecting immune cells in the tumour microenvironment." (PMID 40045162, 2025). "It was proposed that the evaluation of biomarkers characteristic for osteosarcoma cells such as VIM, Ezrin and COL5A2 in blood may be used as a diagnostic and prognostic tool for patients with osteosarcoma." (PMID 37511619, 2023). "Here, our analyses showed that COL5A2 expression was higher in the high-risk group, and increased COL5A2 expression indicated a worse prognosis in osteosarcoma patients, suggesting a potential oncogenic role in osteosarcoma." (PMID 36330451, 2022). "COL5A2, a gene encoding a collagen type V α-2 chain has been associated with extracellular matrix organization, vascularization, EMTs process, invasion and metastasis in colorectal, breast, and bladder cancers, and osteosarcoma." (PMID 34299042, 2021). "COL5A2 expression was shown to be elevated in human osteosarcoma cells, and the downregulation of COL5A2 affected the TGFB and Wnt/β-catenin signaling pathways." (PMID 41373732, 2025). "Subsequent CCK-8 assays, scratch assays, and transwell assays confirmed that enhanced COL5A2 expression contributes to the proliferation, invasion, and migration of osteosarcoma cells." (PMID 35280775, 2022). "All these experiments demonstrated that the upregulation of COL5A2 expression contributes to the promotion of osteosarcoma progression." (PMID 35280775, 2022). "This is consistent with our findings that reveal that enhanced COL5A2 expression accelerated the proliferation, invasion, and migration rate of osteosarcoma cells." (PMID 35280775, 2022). "qRT-PCR and immunofluorescence assays confirmed the high expression of COL5A2 in human osteosarcoma cells." (PMID 35280775, 2022). "The expression of col5a2 in human osteosarcoma MG-63 cells was analyzed by immunofluorescence technique." (PMID 35280775, 2022). "Further experiments should be designed to explore the effects of COL5A2 knockdown or overexpression on RLS3-induced ferroptosis in osteosarcoma cells." (PMID 36330451, 2022). "COL5A2 was reported to be highly expressed in metastatic osteosarcoma, and silencing COL5A2 impaired cell invasion and metastasis by inhibiting the TGF-β and Wnt/β-catenin signaling pathways." (PMID 36330451, 2022). "In this study, we screened COL5A2 for prognostic relevance to osteosarcoma through bioinformatics analysis and demonstrated that COL5A2 inhibited osteosarcoma invasion and metastasis by suppressing the TGF-β signaling and Wnt/β-Catenin signaling pathways." (PMID 35280775, 2022). "After that, FAGs in the turquoise module were utilized to construct a prognostic multigene (COL5A2, HOXB4, and UNC5B) signature for risk stratification in osteosarcoma." (PMID 36330451, 2022). "In this study, the analysis of bioinformatics revealed that COL5A2 indicated a high expression status in metastatic osteosarcoma and led to a poor prognosis." (PMID 35280775, 2022). "Subsequently, human osteosarcoma MG-63 cells were divided into control, COL5A2-enhanced, and COL5A2-knockdown groups and the different expression levels of COL5A2 in MG-63 cells were verified using qRT-PCR with GAPDH as the control gene." (PMID 35280775, 2022). "COL5A2 was significantly expressed in the osteosarcoma metastasis group (P = 0.0089) and its high expression led to a worse prognosis (P = 0.018, HR = 2.2)." (PMID 35280775, 2022). "COL5A2, also known as collagen type V alpha 2 chain, involves in the progression of colorectal cancer, breast cancer, and osteosarcoma." (PMID 31612481, 2020).
osteosarcoma (continued). "Furthermore, qRT-PCR and immunofluorescence assays confirmed the high expression of COL5A2 in human osteosarcoma cells." (PMID 35280775, 2022). "Similarly, the migration ability of osteosarcoma cells was enhanced after transfection with OERNA of COL5A2." (PMID 35280775, 2022). "COL5A2 gene was highly expressed in metastatic osteosarcoma and led to a poor prognosis." (PMID 35280775, 2022). "In addition, the Transwell assay revealed that the upregulation of COL5A2 promoted the invasive effect of osteosarcoma cells." (PMID 35280775, 2022). "In the present study, COL5A2 was the only gene screened for prognostic relevance in patients with osteosarcoma based on whether they were grouped metastatically." (PMID 35280775, 2022). "Thus, we speculated that COL5A2 might participate in the regulation of the ferroptotic process in osteosarcoma." (PMID 36330451, 2022). "According to the Kaplan-Meier (KM) survival analysis of 8 modeled genes, elevated expression levels of COL5A2, COX6A2, UQCRB, SFXN4, FAM162A and MAFF sharply shortened the survival time of osteosarcoma patients." (PMID 39569192, 2024). "We identified three FAGs (COL5A2, HOXB4, and UNC5B) as potential therapeutic targets and important regulators of ferroptosis in osteosarcoma." (PMID 36330451, 2022). "In this study, we further determined that the knockdown of COL5A2 expression inhibited the TGF-β signaling and Wnt/β-catenin signaling pathways, thereby suppressing the invasion and migration of osteosarcoma." (PMID 35280775, 2022). "A total of three FAGs, COL5A2, HOXB4, and UNC5B, were ultimately used to construct a prognostic signature for osteosarcoma." (PMID 36330451, 2022). "We also identified COL5A2, HOXB4, and UNC5B as potential therapeutic targets and important regulators of ferroptosis in osteosarcoma." (PMID 36330451, 2022). "Consistent with the RNA-seq data, the mRNA levels of COL5A2 and HOXB4 were lower and UNC5B mRNA levels were higher in RSL3-treated cells than in control cells, indicating the probable roles of the three FAGs in the ferroptotic processes of osteosarcoma cells." (PMID 36330451, 2022). "In TCGA cohort, Kaplan–Meier survival analysis revealed that increased COL5A2 and UNC5B expression indicated a worse prognosis in patients with osteosarcoma, but HOXB4 expression was not linked with patients’ clinical fate." (PMID 36330451, 2022). "Multivariate Cox regression analysis confirmed that these 8 identified genes, including 2 protective elements (SQOR and PFKFB2) and 6 hazardous factors (MAFF, COL5A2, FAM162A, UQCRB, SFXN4, and COX6A2), could independently predict the overall survival of osteosarcoma samples." (PMID 39569192, 2024). "Osteosarcoma samples were grouped based on whether or not they metastasized and screened by bioinformatics analysis to obtain COL5A2." (PMID 35280775, 2022). "The fact that COL6A3, COL5A2, TNC, and ITGB5 which are highly activated here and part of the focal adhesion-PI3K-Akt signaling axis implies that they are central to osteosarcoma and not simply tissue specific activation." (PMID 34570764, 2021).
breast carcinoma (14 papers, 2013 to 2025). "This is reflected in our 18-gene signature, with three of five RNAs upregulated in PAFs and for which higher expression in breast cancers was associated with poor prognosis encoded collagen proteins (Col5a2, Col13a1, Col18a1)." (PMID 34565423, 2021). "We subsequently assessed the set of INHBA-related genes in breast cancer and found that genes encoding collagens COL10A1, COL12A1, COL5A2 and COL11A1 were associated with INHBA expression." (PMID 41008625, 2025). "According to the xiantao database, COL1A2, COL3A1, FGA, LUM, APOA1, APOH, and COL5A2 were more highly expressed in breast cancer than in normal tissues (p < 0.05), while the opposite pattern was seen for ALB and FBN1 (p < 0.05)." (PMID 37079213, 2023). "In addition to the major fibrillar collagen class, many minor fibrillar collagens, including those (COL11A1, COL5A1, and COL5A2) have reported prognostic value in breast cancer." (PMID 39716322, 2024). "Among the members of the collagen family, COL5A2 is correlated to the progression of breast cancer." (PMID 36505882, 2022). "In a The Cancer Genome Atlas (TCGA) comparative study between normal breast tissue (n = 113) and breast tumors (n = 1109), COL11A1, COL12A1, COL1A1, COL1A2, COL5A1, and COL5A2 transcripts were upregulated in breast cancer and could discriminate between the two breast tissues." (PMID 39716322, 2024). "In the HER2-negative breast cancer cohort treated with Bevacizumab, MMP2, COL5A2, COL6A1, DLK1, and MDK were identified as predictive of treatment response, aligning with their documented roles in angiogenesis and stromal interactions." (PMID 41139924, 2025). "While no increase was found in COL5A2 expression after treatment with β-estradiol or in COL5A2 and LAMA4 after treatment with TGFβ in ER-positive and -negative breast carcinoma cells, respectively, all other gene expression levels increased significantly after treatments." (PMID 23441215, 2013).
ovarian carcinoma (12 papers, 2017 to 2025). A malignant neoplasm originating from the surface ovarian epithelium. "In another study that used robust Bayesian network modeling, 13 hub genes including ARID1A, C19orf53, CSKN2A1, and COL5A2 signature with a prognostic function in ovarian cancer was established." (PMID 34054929, 2021). "A previous study also showed that high expression of COL1A1, COL3A1, COL5A1, and COL5A2 in ovarian cancer promotes tumor immune tolerance and results in poor prognosis." (PMID 34034744, 2021). "In one network analysis of ovarian cancer, COL5A2, TPX2, and BIRIC5 were also identified as hub genes using the joint sparse regression model." (PMID 28562334, 2017). "ECM-receptor interaction was enriched based on the KEGG pathway in our study, while COL3A1, COL5A2, and COL2A1 were regarded as potential ECM components associated with cytostatic drug resistance in ovarian cancer cells." (PMID 28562334, 2017). "The expression of COL3A1, COL5A2, and COL1A2 was also studied by immunocytochemistry and western blot analysis and found to be associated to drug-resistance in ovarian cancer." (PMID 28562334, 2017). "While COL5A2 has been traditionally studied in the context of connective tissue disorders, recent studies have begun to uncover its oncogenic roles in cancers such as ovarian cancer and non-small cell lung cancer (NSCLC)." (PMID 40087784, 2025). "Noticeably, a very recent study showed the higher concentration of lipoprotein lipase (LPL) and collagen type V alpha 2 chain (COL5A2) in exosomes derived from ovarian cancer cells (SKOV-3) compared to ovarian surface epithelial cells (HOSEPiC) by proteomic and lipidomic analysis." (PMID 33671587, 2021). "Moreover, COL3A1, COL5A2 and COL1A2 expression are associated with drug-resistance in ovarian cancer." (PMID 31533654, 2019). "Similar to the mesenchymal subtype from the original TCGA study of ovarian cancer, S‐ECM shows upregulation of genes such as COL5A2, COL1A1, COL3A1, THBS2, COL11A1, COL6A3, and MMP2 that are involved in epithelial‐to‐mesenchymal transformation (EMT) processes, metastasis, and chemoresistance." (PMID 36637997, 2023). "Interestingly, according to the expression profiling based on the parabiosis model of ovarian cancer hematogenous metastasis, four genes (POSTN, LUM, COL3A1, COL5A2) of the LMGS were shown to be significantly up-regulated in the omental metastases generated through a hematogenous route." (PMID 31888563, 2019).
colorectal cancer (11 papers, 2007 to 2024). A primary or metastatic malignant neoplasm that affects the colon or rectum. "A recent study demonstrated that COL5A2 was a key part of tumor progression in colorectal cancer and was associated with poor prognosis in these patients." (PMID 37312060, 2023). "Collectively all these results reveal that the COL11A1 gene has a positive association and correlation with THBS2, COL10A1, COL5A2, and COL1A2 to upregulate the gene expression to induce the development of colorectal cancer." (PMID 33597969, 2021). "COL5A2 is also involved in the carcinogenesis of colorectal cancer." (PMID 34281542, 2021). "Collectively all these experimental data clearly reveal that the COL11A1 gene along with its associated THBS2, COL10A1, COL5A2, and COL1A2 might serve as a prognostic biomarker for colorectal cancer." (PMID 33597969, 2021). "COL5A2 expression was also found in colorectal cancer but not in normal colon, showing that COL5A2 was implicated in the carcinogenesis of colorectal cancer (Fischer, Stenling, Rubio, & Lindblom, 2001)." (PMID 31612481, 2020). "The PathwayMapper tab in cBioPortal servers shows the alteration frequency of COL11A1, THBS2, COL10A1, COL5A2, and COL1A2 over the various pathways on the colorectal cancer dataset using a white to red color scale where the more frequently altering gene shows greater intensity of the red color." (PMID 33597969, 2021).
colon cancer (9 papers, 2013 to 2022). "The expression level of COL5A2 is increased in various types of cancers, such as pancreatic cancer and colon cancer." (PMID 33739392, 2021). "It has recently been observed that Col5a2 is highly expressed in invading neoplastic epithelial cells, and that it is expressed in the human fetal gut and in colon cancer cells." (PMID 23574622, 2013). "COL5A2 was reported to promote proliferation and invasion in colon cancer and prostate cancer." (PMID 35368700, 2022). "The expression of COL5A2 is related to the occurrence and development of colon cancer." (PMID 36447214, 2022). "Collectively, the expression pattern, prognostic effect, immune-inhibitory activity demonstrated the oncogenic effect of COL5A2, EDNRA, and OLR1 in colon cancer." (PMID 31500382, 2019). "Nevertheless, to our knowledge, inhibition of EDNRA or COL5A2 has not been tested for colon cancer treatment." (PMID 31500382, 2019). "Among the upregulated stromal cell-enriched proteins, some proteins have been reported to be potential markers in colon cancer prognosis or tumorigenicity, such as collagen XII (COL12A1), thrombospondin 2 (THBS2), collagen triple helix repeat-containing protein 1 (CTHRC1) and COL5A2." (PMID 26338966, 2015). "It suggests that the hsa-mir-21-5p to COL5A2/OLR1, hsa-mir-135b-5p/hsa-mir-495-3p/hsa-mir-409-3p to COL5A2 and hsa-mir-224-5p/hsa-mir-21-3p/hsa-mir-135b-5p/hsa-mir-495-3p to EDNRA pathways may play substantial roles in regulation of the tumor immune microenvironment in colon cancer." (PMID 31500382, 2019).
prostate carcinoma (8 papers, 2021 to 2024). A carcinoma that arises from epithelial cells of the prostate gland. "COL5A2 was found to enhance the infiltration abundance of tumor-associated macrophages while concurrently diminishing the population of CD8 T cells in prostate cancer." (PMID 39569192, 2024). "Module 2 includes COL3A1, COL5A2, and NOTCH3, which have been reported to be associated with metastasis in prostate cancer, as well as HEYL, STMN2, and ASPN, which have been implicated in prostate cancer progression." (PMID 39347576, 2024). "Third, the mechanisms by which COL5A2 promoted the progression of prostate cancer requires further investigation." (PMID 33816226, 2021). "Besides, Col5a2 could promote proliferation and invasion of prostate cancer and predict recurrence-free survival." (PMID 35964009, 2022).
glioma (7 papers, 2007 to 2023). A benign or malignant brain and spinal cord tumor that arises from glial cells (astrocytes, oligodendrocytes, ependymal cells). "It reported that EMT processes and the immunosuppressive microenvironment in gliomas are regulated by COL5A2." (PMID 37723519, 2023). "The expression levels of COL5A1 and COL5A2 are significantly correlated with glioma progression stage." (PMID 35198102, 2022). "Importantly, we identified that 6 collagen genes (COL1A1, COL1A2, COL3A1, COL4A1, COL4A2, and COL5A2) could regulate the immunosuppressive microenvironment of glioma." (PMID 34034744, 2021). "On the CGGA website (mRNAseq_325), collagen genes (COL1A1, COL1A2, COL3A1, COL4A1, COL4A2, and COL5A2) in WHO grades II, III, and IV glioma samples were analyzed to explore the expression levels of these genes." (PMID 34034744, 2021). "Then, six collagen genes (COL1A1, COL1A2, COL3A1, COL4A1, COL4A2, and COL5A2) were selected for further validation in Oncomine, TCGA (The Cancer Genome Atlas), and CGGA (Chinese Glioma Genome Atlas) database." (PMID 34034744, 2021). "In conclusion, the collagen genes (COL1A1, COL1A2, COL3A1, COL4A1, COL4A2, and COL5A2) could regulate the immunosuppressive microenvironment and be involved in the EMT process of glioma." (PMID 34034744, 2021). "COL5A2 has not reported the roles in glioma progression, but they were reported to participate in various malignancies." (PMID 34034744, 2021).
keloid (6 papers, 2021 to 2025). An irregularly shaped, elevated mark on the skin caused by deposits of excessive amounts of collagen during wound healing. "The diagnostic value of COL1A1, COL1A2, COL3A1, COL5A1, and COL5A2 between keloid and different control tissue was evaluated by different datasets." (PMID 35872873, 2022). "In our study, the results of ENCORI prediction and RT-qPCR showed that miR-29a-3p can regulate the expression of COL1A1, COL1A2, COL3A1, COL5A1, and COL5A2, and these target genes were closely related to the development of keloid." (PMID 35872873, 2022). "When the diagnostic value of these key genes were evaluated between the normal skin from keloid-prone or normal individuals (GSE113619), the AUC values of COL1A1, COL1A2, COL3A1, COL5A1, and COL5A2 in keloid were 0.650, 0.625, 0.575, 0.525, and 0.450, respectively." (PMID 35872873, 2022). "In our present study, we screened bone/cartilage-related genes (COMP, ASPN, COL5A2, COL10A1, and COL11A1), transcription factor (FOXC1), and miRNA (miR-335-5p) in major fibrotic skin diseases including keloid and SSc." (PMID 37082197, 2023). "According to the findings of RNA sequencing, COL5A2, COL10A1, and COL11A1 have been reported to be upregulated in keloid, as in our study." (PMID 37082197, 2023). "It was downregulated in keloid and can negatively regulate the expression of COL1A1, COL1A2, COL3A1, COL5A1, and COL5A2." (PMID 35872873, 2022). "One of the characteristics of the mesenchymal fibroblasts in keloid is the high expression of secretory proteins such as POSTN, COMP, COL11A1, ASPN, and COL5A2." (PMID 34140509, 2021). "Transcriptome analysis showed that the core differentially expressed genes related to collagen synthesis play a vital role in the pathogenesis of keloids, including COL1A, COL1A2, COL5A2, and COL3A1." (PMID 35222522, 2021). "The hub genes of COL1A, COL1A2, COL5A2, and COL3A1 indicate that genes related to collagen synthesis play a vital role in the pathogenesis of keloids." (PMID 35222522, 2021). "In agreement with our interactome, regulation of ELN, COL5A2, FSTL1 and COL1A1 was demonstrated experimentally using a miR-29b mimic and antagomir in primary human skin fibroblasts and other models in the context of treatment of keloid formation and fibroplasia using miR-29b mimic Remlarsen." (PMID 39883689, 2025). "However, there is no research report on the correlation between COL5A1 and COL5A2 expression and keloid so far." (PMID 35872873, 2022).